IDH2 (isocitrate dehydrogenase (NADP(+)) 2)
Diseases named in the same sentence as IDH2 in open-access papers (continued):
Sharing a sentence is not in itself a finding about the gene and the disease.
leukemia (continued). "Importantly, pharmacological inhibition of IDH2 using small chemical compound AGI-6780 also exhibited significant inhibitory effect in AML cell lines and primary leukemia cells isolated from AML patients with wt-IDH2 in vitro and in vivo." (PMID 35313945, 2022). "In multivariate analysis, IDH1 mutations but not IDH2 mutations were associated with shortened leukemia-free survival." (PMID 32859092, 2020). "Using a candidate gene approach, five mutated genes including ASXL1, SRSF2, EZH2, IDH1, and IDH2, which are reported to occur in 25–30% of all PMF patients, were associated with shorter OS and leukemia-free survival (LFS), defining a high-molecular risk (HMR) category." (PMID 31013941, 2019). "Additionally, AG-221, a first-in-class inhibitor of mutant IDH2, leads to 2HG reduction in IDH2 mutant leukemia and survival benefit in primary human IDH2 mutant AML xenografts." (PMID 30356832, 2018). "Notably, AG-211 induced cell differentiation in leukemia cells from IDH2-mutant expressing mice and it synergized with Flt3 inhibition to reduce leukemic cell burden in vivo." (PMID 28092669, 2017). "This Registered Report describes the proposed replication plan of key experiments from “The common feature of leukemia-associated IDH1 and IDH2 mutations is a neomorphic enzyme activity converting alpha-ketoglutarate to 2-hydroxyglutarate” by Ward and colleagues, published in Cancer Cell in 2010." (PMID 26943899, 2016). "IDH2 inhibitors are naturally being developed for IDH2-mutant leukemia, EZH2 inhibitors are being studied in EZH2-altered B-cell lymphoma, and our BET inhibitors are actively being studied in BET-rearranged lung cancer and BET-rearranged head and neck cancer (so-called NUT midline carcinoma)." (PMID 25593599, 2014). "Similarly, IDH2 inhibition in IDH2 mutant leukemia cells elicited a leukemic cell differentiation response, suggesting another avenue that could reverse the differentiation block observed in AML." (PMID 39766049, 2024). "Importantly, inhibition of IDH2 by AGI-6780 exhibited potent cytotoxic effect on primary leukemia cells isolated from AML patients with wt-IDH2, while the same concentrations of AGI-6780 displayed minimum toxicity in normal human bone marrow cells using MTS assay and flow cytometry analysis." (PMID 35313945, 2022). "Indeed, we showed that a specific knockdown of wt-IDH2 led to a potent inhibition of leukemia cell proliferation in vitro and in vivo, indicating that specific abrogation of IDH2 could exert significant therapeutic activity against AML." (PMID 35313945, 2022). "The concurrence of genetic changes in IDH2 and SRSF2 among individuals with AML results in synchronized impacts on the epigenome and RNA splicing, which play a role in the development of leukemia." (PMID 39034387, 2024). "Several genes that we identified included IDH2, NCOA2, IKZF1 and BLM described as being involved in leukemia." (PMID 37174060, 2023). "Amongst pluripotency genes, we have identified cancer genes (IDH2, NCOA2, IKZF1, BLM) which are already described as being involved in leukemia." (PMID 37174060, 2023). "We found that wild-type IDH2 was overexpressed in AML and played a major role in promoting leukemia cell survival and proliferation in vitro and in vivo." (PMID 35313945, 2022). "In leukemia, the IDH1/IDH2 gene restructures the enzyme for isocitrate while increasing the affinity for α-ketoglutarate (αKG) with the production of 2HG." (PMID 35743098, 2022).
leukemia (continued). "It indicates critical role of IDH2 in development and maintenance of AML stem cells and implication of environmental factors in leukemia." (PMID 27183914, 2016). "A substantial decrease in C-MYC protein was detected as early as 6 h after the leukemia cells were exposed to DM-αKG, which did not affect IDH2 protein level." (PMID 35313945, 2022). "Given that JAK2/IDH-mutated mice do not develop overt leukemia, it is possible that IDH1/IDH2 are not key-genes in leukemic transformation but rather SRSF2 is." (PMID 34771693, 2021). "We observed that IDH1/2 VAF in morphologic leukemia free state was not reduced below 2.5% in 15 out of 62 cases (24%, 10 IDH2 R140Q, 3 IDH2 R172K, 1 IDH1 R132H and 1 IDH1 R132C)." (PMID 34153064, 2021).
cholangiocarcinoma (54 papers, 2014 to 2026). A carcinoma that arises from the intrahepatic biliary tree (intrahepatic cholangiocarcinoma) or from the junction, or adjacent to the junction, of the right and left hepatic ducts (hilar cholangiocarcinoma). "The conversion of IDH1 R132C to IDH1 R132F and the acquired isoform mutation of IDH2 R172V have been reported in patients with IDH1-mutated cholangiocarcinoma who develop resistance to ivosidenib as a result." (PMID 39273177, 2024). "A relevant study shows that IDH1 and IDH2 mutations predominate in cholangiocarcinoma, while IDH2 contributes only partially (2–6%)." (PMID 35802554, 2022). "One of the most common gene mutations in cholangiocarcinoma is affecting the IDH1/IDH2 gene (encoding isocitrate dehydrogenase isotypes), which is characteristic of the IHCC category." (PMID 35008396, 2022). "IDH2 mutations have been reported in cholangiocarcinoma, an aggressive cancer associated with epithelial cells lining the bile duct." (PMID 33981605, 2021). "The discovery of mutations in IDH isoforms (IDH1 and IDH2) has been a major breakthrough in the translational research of cholangiocarcinoma." (PMID 33182517, 2020). "The identification of cholangiocarcinoma patients with IDH1/IDH2 variants, which are mutually exclusive, may benefit from targeted therapies." (PMID 40075667, 2025). "Therefore, gain-of-function mutations in IDH1 or IDH2 are important triggering events in the development of cholangiocarcinoma." (PMID 35154988, 2022). "Notably, IDH1 and IDH2 mutations, which are common (approximately 25%) in cholangiocarcinoma (CCA) patients of Western populations 21, were observed in only 7% and 2% of Chinese BTC patients, respectively." (PMID 33754015, 2021). "Enasidenib is an IDH2 inhibitor, and it is currently under investigation in a phase I/II trial for solid tumors, including cholangiocarcinoma (NCT02273739)." (PMID 38203635, 2023). "To date, dozens of small molecules of IDH1/IDH2 inhibitors are under investigation, of which ivosidenib (AG-120) has been approved for the treatment of IDH1 mutated cholangiocarcinoma and acute myeloid leukaemia." (PMID 37980418, 2023). "One case of conversion of IDH1 R132C to IDH1 R132F, and one case of isoform switching to mutant IDH2, have been reported in patients with IDH1-mutated cholangiocarcinoma who developed resistance to ivosidenib." (PMID 36056177, 2022). "Additional efforts to test the combination of olaparib and AZD6738 is underway in phase II trial in IDH1- and IDH2-mutant cholangiocarcinoma and solid tumors, led by LoRusso and colleagues at our institution (NCT03878095)." (PMID 34027408, 2021). "Two IDH inhibitors, ivosedinib (an IDH1 inhibitor) and enasedinib (an IDH2 inhibitor) demonstrated efficacy against gliomas, cholangiocarcinomas, and AML in clinical trials." (PMID 34831002, 2021). "Additionally, FDA-approved drugs like ivosidenib and enasidenib targeting IDH1 and IDH2, respectively, demonstrated clinical efficacy in IDH-mutated AML, glioma, and cholangiocarcinoma, either alone or in combination." (PMID 38003566, 2023). "Approximately 20% of cholangiocarcinomas harbor IDH1 and IDH2 mutations; ivosidenib has been approved for treating IDH1-mutant CCA." (PMID 39610917, 2024). "As previously discussed, IDH1 and IDH2 mutations establish an immunologically cold background with low lymphocyte infiltrates at the tumor site; the treatment with Ivosidenib has been proved to be able to recruit CD8+ T cells and restore immune system tumor vulnerability in cholangiocarcinoma." (PMID 39123479, 2024). "Alterations in chromatin remodeling genes (ARID1A, BAP1, IDH1, IDH2, PBRM1, SMARCB1) were found in 30.7% (47/153) of cancers in our series, confirming recent reports on the significant involvement of these genes in cholangiocarcinoma." (PMID 24867389, 2014).
cholangiocarcinoma (continued). "Eight of them had not been detected by routine testing (FANCA p.W911Dfs*31 in GE02 pancreatic cfDNA, 3 NRAS p.Q61K in GE17 and GE15 melanoma and in GE11 cholangiocarcinoma, a NRAS p.G13D in GE22 pancreatic cancer, an IDH2 p.R172S in GE11 cholangiocarcinoma, and an IDH2 p.R140Q in GE14 melanoma)." (PMID 38750555, 2024).
breast cancer (37 papers, 2013 to 2026). A primary or metastatic malignant neoplasm involving the breast. "The presence of IDH2 has been linked to the aggressive behavior of breast cancer through its promotion of cell proliferation." (PMID 39150915, 2024). "Microarray and proteomic analysis identified high levels of IDH2 to be a factor of poor overall survival in breast cancer, but the underlying mechanisms remain elusive." (PMID 38658533, 2024). "The increase in IDH2 mRNA expression in breast cancer seemed notably associated with genomic DNA amplification and the gain of copy number in TNBC." (PMID 38658533, 2024). "In fact, IDH2 is significantly lower expressed in normal tissue compared to tumor, and lower IDH2 expression is associated with better relapse-free survival in other breast cancer cohorts." (PMID 38965614, 2024). "Furthermore, IDH2 has been evaluated as an independent risk factor for shorter breast cancer specific-survival based on the transcriptomic and proteomic analysis of IDH2 expression in breast cancer tissue microarrays." (PMID 38167476, 2024). "In breast cancer, IDH2 was reported to contribute to cell proliferation, anchorage-independent growth, glycolysis, mitochondrial respiration, and antioxidant defense, and be associated with an aggressive phenotype of breast carcinoma." (PMID 38167476, 2024). "The authors further demonstrated that SIRT3 loss reduced IDH2 activities by decreasing IDH2 dimerization and that IDH2 acetylation at lysine 413 impairs mitochondrial respiration and detoxification, increases ROS production, and correlates with Luminal B breast cancer risk." (PMID 36291902, 2022). "A recent study using labeled glutamine experiments showed that suppression of IDH2 in breast cancer cells decreased reductive carboxylation of AKG in the TCA cycle and increased AKG levels." (PMID 40863152, 2025). "SIRT3 regulated IDH2 dimerization by mediating Lys413 site acetylation of IDH2, which regulated the metabolism and progression of breast cancer." (PMID 40421455, 2025). "Although IDH2 genes are rarely mutated in breast cancer, nearly 35% of cases either have IDH2 amplification or mRNA overexpression, and it appears that IDH2 expression is correlated with worse prognosis in primary breast cancer." (PMID 38965614, 2024). "Through the analysis of genomic datasets, the authors revealed that wild-type IDH2 mRNA expression was significantly elevated in breast cancer, particularly in TNBC, correlating with advanced clinical stages." (PMID 39409901, 2024). "The increased IDH2 mRNA in breast cancer was most notable in the basal type and appeared positively correlated with clinical stages." (PMID 38658533, 2024). "In the context of breast cancer, upregulation or mutation of the mitochondrial NADP-dependent enzyme IDH2 has been associated with disease progression and prognostics." (PMID 39150915, 2024). "Further, we used Clinical Proteomic Tumor Analysis Consortium and the International Cancer Proteogenome Consortium datasets to further explore IDH2 protein expression levels among different subtypes of breast cancer." (PMID 38413708, 2024). "Our analysis of the Cancer Genome Atlas (TCGA) datasets and Gene Expression Omnibus (GEO) revealed that wild-type IDH2 mRNA expression was significantly elevated in breast cancer compared with normal tissues." (PMID 38658533, 2024). "IDH2 exerts a significant influence on the progression of multiple cancers, including breast cancer." (PMID 38238853, 2024). "Our results show that GDF5, BAHCC1, LCN2, FGF14-AS2, and IDH2 are among the top five most effective mRNAs involved in lymph node metastasis of breast cancer based on their SHAP values." (PMID 39150915, 2024). "GEPIA database analysis revealed that IDH2 expression was greater in breast cancer than in normal tissue." (PMID 38238853, 2024).
breast cancer (continued). "The wild-type IDH2 and its elevated expression potentially play a critical function in the progression of breast cancer and the emergence of lymphovascular invasion and metastasis." (PMID 39150915, 2024). "Wild-type IDH2 has been identified as a prognosis marker and potential therapeutic target in breast cancer." (PMID 38167476, 2024). "According to a recent study, loss of SIRT3 promotes acetylation of IDH2 at lysine 413 and subsequent dimerization of IDH 2 in breast cancer cell lines." (PMID 35571098, 2022). "In this study, we aimed to analyze the conditions that lead to maximum 2HG production by wild-type IDH2 in breast cancer cells and to gather background information regarding cellular 2HG turnover." (PMID 33916579, 2021). "We clearly distinguish the IDH2-dependent and independent production of 2HG in mitochondria and demonstrate the active competition between the 2HG producing machinery in mitochondria, namely ADHFE1 and IDH2 in breast cancer cells in vitro." (PMID 33916579, 2021). "Previously, it was suggested that Sirt3 silencing, consequent IDH2 hyper-acetylation, and inactivation, slightly reduced viability and increased the cytotoxicity of cisplatin and tamoxifen in breast cancer cell lines, due to an increase in ROS production." (PMID 31010244, 2019). "First, we examined the expression levels of IDH1 and IDH2 in breast cancer tissues and adjacent normal tissues from 10 patients using western blotting." (PMID 29661250, 2018). "This study aimed to determine whether inhibiting IDH2 enhances sensitivity to proteasome-targeting agents across breast cancer subtypes." (PMID 41681843, 2026). "In addition, breast cancer patients with high IDH2 levels had a worse prognosis in overall survival (OS), recurrence free survival (RFS), and distant metastasis-free survival (DMFS)." (PMID 38238853, 2024). "Interestingly, we found that D-mannose treatment significantly decreased the expression level of IDH2 in human breast cancer cell line MDA-MB-231 and MCF-7." (PMID 38167476, 2024). "Interestingly, expression profile analysis revealed even higher levels of IDH2 mRNA in HER2-positive breast cancer compared to TNBC, which warrants further investigation." (PMID 39409901, 2024). "Notably, IDH2 was found to be significantly upregulated in stage 3 breast cancer tissues and cell lines." (PMID 39150915, 2024). "In this study, we found that D-mannose treatment can promote the degradation of IDH2 protein in mammary cancer cells by upregulating the E3 ligase RNF185, rendering the tumor cells more vulnerable to pro-oxidant treatment and inhibiting the proliferation of breast cancer cells." (PMID 38167476, 2024). "Therefore, wildtype IDH2 is a potential target for clinic treatment of breast cancer, and further studies about the regulation of IDH2 and drugs targeting this regulation are warranted." (PMID 38167476, 2024). "A deregulation of the isocitrate dehydrogenase enzyme isoforms 1 (IDH1) and 2 (IDH2) in the epithelial component of breast cancer tumors could be related to these findings." (PMID 36831625, 2023). "We investigated whether production of mitochondrial 2HG is elevated in breast cancer cell lines and identified active competition for initial substrate, 2OG, between enzymes isocitrate dehydrogenase IDH2 and alcohol dehydrogenase ADHFE1." (PMID 33916579, 2021). "We tested six breast cancer cell lines using gas chromatography coupled with mass spectrometry (GC-MS) and revealed distinct levels of 2HG with maximal production in Hs578T cell line, which paradoxically expresses low levels of IDH2." (PMID 33916579, 2021). "Previously, we have demonstrated that 2HG can be formed by mitochondrial wild-type IDH2 despite the absence of any IDH2/1 mutations in breast cancer cells." (PMID 33916579, 2021). "In view of the development of IDH2 mutation inhibitors, IDH2 mutations in SPCRP may become a new target for breast cancer treatment and intervention." (PMID 33981605, 2021).